TLR2 (toll like receptor 2)
Diseases named in the same sentence as TLR2 in open-access papers (continued):
Sharing a sentence is not in itself a finding about the gene and the disease.
pneumococcal infection (19 papers, 2005 to 2024). Infections with bacteria of the species streptococcus pneumoniae. "More precisely, TLR2 and -13 emerged as the primary sensors for detecting pneumococcal infections in murine CSF." (PMID 38358825, 2024). "The protective role of TLR2, TLR4, and TLR9 against pneumococcal infection is suggested by the results obtained from studies using either TLR2, TLR4, or TLR9 knockout or mutant mice." (PMID 35281442, 2022). "Upon pneumococcal infection, a considerate amount of Siglec-5 and TLR-2 were recruited to the raft fractions 4 and 5, and a significantly reduced raft translocation of Siglec-5 was observed in the WT SPN-infected cells." (PMID 33777832, 2021). "For instance, TLR2 signaling was shown to be important for enabling a Th1-related IgG response to pneumococcal infection in mice." (PMID 32560374, 2020). "Since TLR2 signaling augments the interferon response by human nasopharyngeal epithelial cells during mono-pneumococcal infection, it is unclear how these two pathways mediate the outcomes of pneumococcal microinvasion, colonization, or progression to disease in people." (PMID 38629841, 2024). "Although macrophages respond to pneumococcal infections by activating TLR2 signaling pathways, it is unknown if nasopharyngeal epithelial cells respond in the same way." (PMID 38629841, 2024). "Thus, control of pneumococcal infection in the central nervous system apparently depends on the additive, cooperative activity of multiple cell surface (TLR2) and endosomal (TLR7, TLR9, and TLR13) receptors." (PMID 32209688, 2020). "Since TLR2 has been classically considered the most important receptor involved in the recognition of Gram-positive bacteria, several studies have addressed its role in experimental pneumococcal infections in mice." (PMID 32209688, 2020). "The main TLRs involved in pneumococcal infections are TLR2, TLR4, and TLR9." (PMID 29988379, 2018). "In addition, it is involved in the TLR2/NF-κB pathway by suppressing the expression of TLR2/NF-κB p65 in lung tissue with mouse pneumococcal infection." (PMID 30071688, 2018). "TLR2 is necessary in pneumococcal infection because it recognizes bacterial cell wall constituents." (PMID 29988379, 2018). "Given that NanA reduces the surface sialylation of infected cells and binding of Siglec to its sialyl ligands is necessary for its raft localization, we then investigated whether NanA has any effect on the translocation of TLR-2 and Siglec-5 into lipid rafts upon pneumococcal infection." (PMID 33777832, 2021). "Moreover, TLR2 is the main PRR recognizing gram-positive bacteria, and recent studies have shown that TLR2 -deficient animals are at high risk for succumbing to invasive pneumococcal infections." (PMID 16004610, 2005). "In each experiment, we included for comparison mice lacking MyD88 or TLR2, each of which has been previously studied in similar models of pneumococcal infection." (PMID 32209688, 2020). "The innate immune response of TLR2/TLR4 double-knockout mice to intracisternal pneumococcal infection was more severely impaired than that of mice lacking only TLR2 or TLR4." (PMID 22662111, 2012). "Interestingly TLR2/CD14 KO mice produced less TNF than wt mice, which indicates that besides TLR2 as the major regulator, CD14 participates in a temporally and locally coordinated action in controlling TNF during pneumococcal infection." (PMID 17428319, 2007). "The indistinguishable disease phenotypes of Tlr2/13–/– and Tlr2/4/13–/– mice, along with their similarity to the Myd88–/– disease phenotype, suggest that TLR2 and -13 are the primary drivers of innate immune activation during pneumococcal infection of the murine CNS." (PMID 38358825, 2024).
acute kidney injury (18 papers, 2009 to 2025). Sudden and sustained deterioration of the kidney function characterized by decreased glomerular filtration rate, increased serum creatinine or oliguria. "Extracellular histones contribute to the development of acute kidney injury by directly releasing proinflammatory cytokines via TLR2/4." (PMID 40356926, 2025). "Another study demonstrated that Toll-like receptor 2 (TLR2) promotes autophagy in renal tubular epithelial cells via the PI3K/Akt signaling pathway following cisplatin-induced acute kidney injury." (PMID 39996754, 2025). "Extracellular histones can interact with TLR2, TLR4 and TLR9 to cause organ damages in acute kidney injury and sterile inflammatory liver injury." (PMID 32432055, 2020). "In LPS treated renal tubular epithelial NRK-52E cells (AKI), emodin also inhibited LPS-induced TLR2, NF-κB, TNFα, IL-1β and IL-6 expression in vitro, which may contribute to the immune regulation of emodin in LPS-induced acute kidney injury." (PMID 35744949, 2022). "Both diabetic patients with or without kidney failure and non-diabetic patients with renal failure had increased TLR2 and TLR4 mRNA expression in association with increased levels of proinflammatory cytokines (TNF-α, IFN-γ, and IL-6) compared to normal subjects." (PMID 33442388, 2020). "Extracellular histones can induce microvascular endothelial injury and the TLR2/4-mediated inflammation can lead to acute tubular necrosis in acute kidney injury (AKI)." (PMID 28316860, 2017). "Moreover, emodin attenuates inflammation by inhibiting the TLR2-mediated NF-κB signaling pathway, which may contribute to the regulatory effects of emodin on the immune system and inflammation in models of LPS-induced acute kidney injury." (PMID 32910199, 2020). "Recent work has clearly demonstrated the induction of inflammatory responses by extracellular histones from dying cells via TLR2 and TLR4 in acute kidney injury." (PMID 24454474, 2013). "Several studies document a similar role for TLR2, TLR4, and MyD88 in postischemic acute renal failure of C57BL/6 mice." (PMID 21544241, 2011). "Indeed, another study shows that danger signals from necrotic tubular epithelial cells could activate the NOD-like receptor protein 3 (NLRP3) inflammasome in macrophages through the TLR2/caspase 5/Panx1 axis during acute kidney injury (AKI)." (PMID 36555574, 2022). "Therefore, our studies’ overexpression of TLR2 and TLR4 and oxidative stress synergistically progresses acute lung injury induced by acute kidney injury." (PMID 35911649, 2022). "Moreover, TLR-2 and TLR-4 plays an imperative role in the pathophysiology of acute kidney injury and may be a potential therapeutic target to lessen renal damage in response to various pathological stimuli." (PMID 37045926, 2023). "In addition to HMGB1, histones released from damaged renal cells in acute kidney injury (AKI) triggered neutrophil recruitment and renal inflammation via interaction with TLR2 and TLR4, in turn activating MyD88, NF-κB and mitogen activated protein kinase (MAPK) signaling." (PMID 32731558, 2020). "Following acute kidney injury, pulmonary TLR4 and TLR2 up-regulated significantly in non-treatment (BIR and BNX) groups compared with the sham group but decreased in the treatment (BIR+BMSCs and BNX+BMSCs) groups in comparison." (PMID 35911649, 2022). "TLR2 and TLR4 expressions are much more elevated in nephrotic diabetic patients with renal failure compared to nephrotic diabetic patients without renal failure." (PMID 33442388, 2020). "In conclusion, TLR2 and TLR4 expressions are elevated in nephrotic diabetic patients with renal failure or without renal failure compared to normal individuals." (PMID 33442388, 2020).
Crohn disease (18 papers, 2007 to 2026). A gastrointestinal disorder characterized by chronic inflammation involving all layers of the intestinal wall, noncaseating granulomas affecting the intestinal wall and regional lymph nodes, and transmural fibrosis. "In addition, NOD2 helped to mediate immune tolerance and homeostasis by inhibiting TLR2/4-mediated induction of inflammatory cytokine production, which is strongly associated with Crohn’s disease (CD)." (PMID 34971392, 2022). "In conclusion our case-control association study revealed no significant role of the functional relevant polymorphisms in TLR2, the GTn microsatellite repeat polymorphism in intron 2 and the Arg753Gln in the susceptibility to Crohn’s disease or ulcerative colitis." (PMID 28388655, 2017). "Overall, the frequency for carriers of shorter GTn repeats in intron 2 of the TLR2 gene, which have previously been associated with low TLR2 expression and high IL-10 production, was slightly elevated in Crohn’s disease and ulcerative colitis compared to healthy controls (16.0% resp." (PMID 28388655, 2017). "NOD2 is the strongest associated Crohn's susceptibility gene and Crohn's disease patients who express NOD2 polymorphisms display loss of function for induction of NOD2 effector genes and NOD2/TLR2 specific genes." (PMID 31114588, 2019). "Compared to control cells, crypt epithelial cells isolated from active ulcerative colitis and Crohn's disease colonic mucosal samples showed significantly higher expression of TLR-2 and TLR-4 transcripts and protein (on the cell surface)." (PMID 24828022, 2014). "Compared to histologically normal controls, crypt epithelial cells isolated from colonic mucosal samples affected by ulcerative colitis and Crohn's disease demonstrated enhanced expression of TLR-2 and TLR-4 transcripts and cell surface protein." (PMID 24828022, 2014). "TLR2 will provide a candidate of predictors in the Crohn’s disease anti-TNFα therapy." (PMID 35517818, 2022). "Moreover, after tSNE reanalysis of TLR2 expression and cell types in public single-cell sequencing data of Crohn’s disease patients." (PMID 35517818, 2022). "Finally, we examined DCs from patients with Crohn's disease expressing associated NOD2 variants and found they were unable to induce cross-presentation following NOD2 and TLR2 triggering." (PMID 31114588, 2019). "Interestingly, previous studies have shown that TLR2 G753A SNPs are associated with urinary tract infection, TLR4 C399T SNPs are associated with various infections and Crohn's disease, and TLR9 G2848A SNPs are associated with cervical cancer." (PMID 30116270, 2018). "The two functional relevant polymorphisms in TLR2, the GTn microsatellite repeat polymorphism in intron 2 and the Arg753Gln variant do not seem to play a role in the susceptibility to Crohn’s disease or ulcerative colitis." (PMID 28388655, 2017). "There could also be a connection of Nod2 to Crohn's disease as muramyl dipeptide (MDP) protects mice from experimental colitis by down regulating TLR2 and other TLRs in DCs." (PMID 20949035, 2010). "In the study, bioinformatics and experimental research identified TLR2, TREM1, CXCR1, FPR1, and FPR2 as promising candidates for predicting the anti-TNFα response in patients with Crohn’s disease and especially TLR2 as a core predictor." (PMID 39062093, 2024). "In theterminal ileum, a significant increase of TLR2 expression and an up-regulation of TLR4 havebeen reported in patients with active ulcerative colitis and Crohn's disease respectively." (PMID 23028414, 2012). "Furthermore, mycobacterial TLR2 and NOD2 agonists synergistically induce cytokine release in PBMCs obtained from healthy volunteers and patients with Crohn's disease." (PMID 17705850, 2007).
Crohn disease (continued). "The aim of our studies was to investigate the expression of Toll-like receptor (TLR)-2 and TLR-4 (and in some studies TLR-5) in myofibroblasts and small and large intestinal crypt epithelial cells from control patients and those affected by Crohn's disease and ulcerative colitis." (PMID 24828022, 2014). "It has been suggested that the inflammatory response seen in Crohn's disease results from the inability of toll-like receptor-2 (TLR-2) to become tolerant to its ligand in the absence of appropriately functioning NOD2, resulting in upregulation of proinflammatory cytokines." (PMID 23119165, 2012). "This situation would be similar to the role of NOD2 in Crohn's disease, in which wild type NOD2, also a member of the NLR family, inhibits TLR2 (toll-like receptor-2) activation by peptidoglycan, while mutated NOD2 fails to inhibit TLR2, leading to chronic inflammation in the bowel." (PMID 20041150, 2009).
depression (18 papers, 2015 to 2025). "Regarding TLR2, network analyses have identified it as a key hub gene implicated in both depression and suicidal behavior." (PMID 40558558, 2025). "We found that the E protein caused neuroinflammation by activating TLR2 and led to depression-like behaviors and dysosmia." (PMID 37158916, 2023). "Moreover, TLR2 is associated with depression and conditions such as MDD, and TLR2 inhibition may be a viable target for MDD treatment." (PMID 39408923, 2024). "This increase was normalized following antidepressant treatment, suggesting a potential link between TLR2 and immune dysregulation in depression." (PMID 40558558, 2025). "Given that TLR2 was upregulated among three brain regions and its crucial role in microglia function, we further investigated the distribution and role of TLR2 in E-related depression-like behaviors and dysosmia." (PMID 37158916, 2023). "TLR2 was pharmacologically blocked to determine its role in E protein-related depression-like behaviors and dysosmia in mice." (PMID 37158916, 2023). "Recently, we found that TLR2/4 in microglia in the medial prefrontal cortex (mPFC) is crucial for social avoidance, one of the depression-related behaviors, induced by repeated social defeat stress." (PMID 37443823, 2023). "HMGB1, a putative ligand for TLR2/4, has been suggested to promote depression-related behaviors under acute stress." (PMID 37443823, 2023). "Mice that have been injected with a viral vector leading to TLR2/TLR4 double knockdown in the microglia of the prefrontal cortex are resistant to defeat-induced depression." (PMID 31819042, 2019). "Tomoyuki Furuyashiki (Kobe) initially discovered that TLR2 and -4 are activated in mouse microglia during the repeated social defeat-induced depression." (PMID 31819042, 2019). "Taken together, our results suggest that the TLR2 pathway is a promising therapeutic target for depression, and GSP1-111 could be a novel therapeutic candidate for various neurological disorders." (PMID 39408923, 2024). "Additionally, TLR4 knockout mice exhibited pronounced depression-like behavior, while TLR2 knockout mice showed significant impairment in recovery from depression in the male mice." (PMID 39408923, 2024). "Administration of the inflammasome inhibitors VX-765, E2 and ERβ agonists to ovariectomized mice blocked these signaling pathways by inhibiting P2X7R, TLR2 and TLR4 expression, thereby reversing depression and anxiety-like behaviors caused by estrogen deficiency." (PMID 38898454, 2024). "We hypothesized that the E protein triggered neuroinflammation and evoked depression-like behaviors and dysosmia symptoms via TLR2 in CNS." (PMID 37158916, 2023). "Finally, RT-PCR and immunohistochemistry suggested that TLR2 was upregulated in the cortex, hippocampus and olfactory bulb, the blocking of which mitigated depression-like behaviors and dysosmia induced by E protein." (PMID 37158916, 2023). "Overall, these results revealed that blocking TLR2 could alleviate E-induced dysosmia and depression-like behaviors." (PMID 37158916, 2023). "In a mouse model of depression induced by a strong pathogen lipopolysaccharide (LPS), the expression of Toll-like receptor 2 in microglia was evidently increased, while RNA levels of neuroinflammatory factors, such as IL-1β and IL-6, in the cortex and hippocampus were significantly enhanced." (PMID 33192466, 2020). "Accordingly, we suggest that TLR2 could be a potential therapeutic target in depression treatment." (PMID 39408923, 2024). "In addition, our findings may provide evidence supporting TLR2 as a potential therapeutic target in depression." (PMID 39408923, 2024). "Our CytoHubba analysis identified six hub genes (PECAM1, TLR2, PTGS2, LRRK2, HCK, and IL18), all significantly upregulated in both depression and hypovitaminosis D, with PTGS2 having the highest inference score and reference count." (PMID 38256187, 2024).
depression (continued). "TLR4 and TLR2 were upregulated in peripheral blood samples of IBS patients, especially in IBS patients with depression." (PMID 39749341, 2024). "TLRs, especially TLR2 and TLR4, were found to participate in neurodegenerative diseases such as AD, PD, and ALS, as well as in neuropsychiatric diseases such as depression." (PMID 39408923, 2024). "CREB1, a transcription factor regulating depression-related genes, is influenced by stress and inflammatory responses, with Amuc_1100Δ80 potentially modulating the 5-HTR1A-CREB-BDNF pathway via toll-like receptor 2 (TLR2) interactions." (PMID 40108902, 2025). "Elevated levels of TLR2 may lead to suicidality in patients with MDD, and depression patients experience a decrease in TLR2 levels after treatment." (PMID 39713769, 2024). "Whether other TLR2/4 ligands, such as S100A8/A9, exert pro-depression-like actions together with HMGB1 in the mPFC remains to be examined." (PMID 37443823, 2023). "The present study shows that TLR2 and TLR4 mRNAs in DP-IBS patients are higher than in the control group, which indicates that TLR participates in the inflammation reaction in IBS and depression." (PMID 27478433, 2016). "However, as TLR2/4-mediated microglial activation in the mPFC is crucial for social avoidance induced by repeated social defeat stress, extracellular HMGB1 in selective brain regions, such as the mPFC, could promote depression-like behaviors." (PMID 37443823, 2023). "CRF1, CRF2, TLR2, and TLR4 in IBS patients with depression are significantly higher than those without depression and controls." (PMID 27478433, 2016).